SMTNL2 (smoothelin like 2)
Synonyms: FLJ42461
Tractability: No criterion of Open Targets' tractability assessment is met for any kind of drug.
Gene: Protein-coding gene on chromosome 17 (4,583,999 to 4,608,319, forward strand). Ensembl gene ENSG00000188176.
Subcellular location (Human Protein Atlas): Nuclear speckles; Nucleoplasm
Gene Ontology:
Biological process: actin cytoskeleton organization
Genetic constraint (gnomAD): Loss-of-function variants: 43 observed, 37.02 expected, observed/expected ratio (o/e) 1.16, 90% interval 0.91 to 1.5. The synonymous counts are far from expectation, so gnomAD's model fits this gene poorly and the ratio says little. Missense variants: 646 observed, 574.17 expected, observed/expected ratio (o/e) 1.13, 90% interval 1.05 to 1.2. Synonymous variants: 317 observed, 236.61 expected, observed/expected ratio (o/e) 1.34, 90% interval 1.22 to 1.47.
Homologues: Orthologues: chimpanzee SMTNL2 (98% identical), macaque SMTNL2 (95% identical), rabbit SMTNL2 (86% identical), mouse Smtnl2 (84% identical), rat Smtnl2 (84% identical), pig SMTNL2 (82% identical), dog SMTNL2 (76% identical), guinea pig SMTNL2 (75% identical), tropical clawed frog smtnl2 (47% identical), zebrafish smtnl (45% identical), Caenorhabditis elegans T15B12.1 (18% identical). Paralogues in human: SPTBN1 (16% identical), SPTB (16% identical), SPTBN4 (16% identical), DST (15% identical), SPTBN2 (15% identical), MACF1 (15% identical), PLEC (15% identical), SYNE1 (14% identical), FLNA (13% identical), UTRN (13% identical), SPTBN5 (13% identical), SYNE2 (13% identical), and 24 more.
Diseases named in the same sentence as SMTNL2 in open-access papers:
SMTNL2 is named in the same sentence as 10 diseases in open-access papers, as found by Europe PMC text mining. Sharing a sentence is not in itself a finding about the gene and the disease. The quoted sentences say what the papers report.
co-infection (1 paper, 2025). "Regarding the co-infection of cells by E. coli and S. aureus, the unique genes of ES2 are DZIP1 and SMTNL2; the unique genes of ES3 are ALDH4A1, DNASE1L1, FAM227A, and KAT2B; and ES1 has 143 unique genes." (PMID 40771952, 2025).
heart failure (1 paper, 2023). Inability of the heart to pump blood at an adequate rate to meet tissue metabolic requirements. "However, only SDSL showed an AUC value greater than 0.7 in the test set, whereas EGFL7, SMTNL2, MFAP4, TAGLN, SGPP2 and SMTNL2 showed AUC values greater than 0.5, so SDSL may be a high risk factor in patients with heart failure." (PMID 38250028, 2023). "The analysis revealed that heart failure samples had significantly higher expression levels of EGFL7, SDSL, PPP1R13l, SMTNL2, MFAP4, and TAGLN genes, which may promote the development of heart failure." (PMID 38250028, 2023).
Hypertension (1 paper, 2025). The presence of chronic increased pressure in the systemic arterial system. "Smtnl2 promotes epithelial morphogenesis by stabilizing actin filaments and binds tropomyosin, which is involved in vasoconstriction and contributes to hypertension." (PMID 40275631, 2025).
kidney cancer (1 paper, 2020). Primary or metastatic malignant neoplasm involving the kidney. "In the predicted target gene interrogation interface of the miR-326 3p-arm, SMTNL2 was found to have approximately 20-fold downregulation and satisfactory scores for miRDB and targetScan, which are known to be downregulated in kidney cancer." (PMID 31950188, 2020).
lung carcinoma (1 paper, 2019). "The two other mutations predicted as deleterious, ARHGEF5 and SMTNL2, are linked to a poor prognosis in lung cancer patients, epithelial-mesenchymal transition (EMT), and Rho-GTPase signaling." (PMID 31323891, 2019).
SMTNL2 also shares sentences with these, for which no sentence is quoted: breast carcinoma (1 paper); choroid plexus papilloma (1); head and neck squamous cell carcinoma (1); invasive breast carcinoma (1); tumor (1).